ZNF611 (zinc finger protein 611)
Description:
May be involved in transcriptional regulation.
Synonyms: MGC5384
Tractability: PROTAC: UniProt records ubiquitination sites on it; ubiquitination databases record sites on it.
Gene: Protein-coding gene on chromosome 19 (52,702,813 to 52,735,080, reverse strand). Ensembl gene ENSG00000213020.
Subcellular location: Nucleus
Pathways (Reactome):
Gene expression (Transcription): Generic Transcription Pathway
Gene Ontology:
Molecular function: DNA-binding transcription factor activity, RNA polymerase II-specific; RNA polymerase II cis-regulatory region sequence-specific DNA binding; sequence-specific DNA binding
Biological process: regulation of transcription by RNA polymerase II; positive regulation of DNA-templated transcription; regulation of DNA-templated transcription
Cellular component: nucleus; chromosome
Genetic constraint (gnomAD): Loss-of-function variants: 6 observed, 8.98 expected, observed/expected ratio (o/e) 0.67, 90% interval 0.37 to 1.32. That is too few expected variants to judge how well the gene tolerates losing a copy. Missense variants: 874 observed, 865.12 expected, observed/expected ratio (o/e) 1.01, 90% interval 0.95 to 1.07. Synonymous variants: 262 observed, 286.84 expected, observed/expected ratio (o/e) 0.91, 90% interval 0.82 to 1.01.
Homologues: Orthologues: chimpanzee ZNF611 (98% identical), macaque ZNF611 (86% identical). Paralogues in human: ZNF600 (89% identical), ZNF534 (45% identical), ZNF28 (42% identical), ZNF595 (40% identical), ZNF320 (40% identical), ZNF708 (38% identical), ZNF726 (38% identical), ZNF33B (38% identical), ZNF658 (38% identical), ZNF724 (38% identical), ZNF836 (38% identical), ZNF85 (37% identical), and 164 more.
Diseases named in the same sentence as ZNF611 in open-access papers:
ZNF611 is named in the same sentence as 3 diseases in open-access papers, as found by Europe PMC text mining. Sharing a sentence is not in itself a finding about the gene and the disease. The quoted sentences say what the papers report.
breast carcinoma (1 paper, 2019). "In the analysis for RFS, differential expression of ZNF611, ZNF304, RIPK1, DUSP8, TNFRSF21 and HRAS genes was associated with outcome for breast cancer patients who received radiotherapy." (PMID 30938061, 2019). "Therefore, we propose that the dual function of miR‐122 in the isogenic model of radioresistant breast cancer cells could be result of transcriptional reprogramming controlled by the modulation of ZNF611 and ZNF304 by miR‐122." (PMID 30938061, 2019).
tumor (2 papers, 2019 to 2020). "In this sense, we evaluated the prognostic value of the ZNF611, ZNF304, RIPK1, TNFRSF21, DUSP8 and HRAS genes according to tumor subtypes." (PMID 30938061, 2019).
ZNF611 also shares sentences with these, for which no sentence is quoted: cancer (1 paper).